PPIAP17 (peptidylprolyl isomerase A pseudogene 17)
Synonyms: bA494B22.1; PPIP11
Gene: Processed pseudogene on chromosome 20 (16,223,750 to 16,224,535, reverse strand). Ensembl gene ENSG00000225622.
Diseases named in the same sentence as PPIAP17 in open-access papers:
PPIAP17 is named in the same sentence as 2 diseases in open-access papers, as found by Europe PMC text mining. Sharing a sentence is not in itself a finding about the gene and the disease.
PPIAP17 shares sentences with these, for which no sentence is quoted: colorectal cancer (1 paper); colorectal tumors (1).